TAFA1 (TAFA chemokine like family member 1)
Description:
Regulatory factor which is ligand for CMKLR2 and is involved in the modulation of neural stem-cell proliferation and differentiation.
Synonyms: FAM19A1; TAFA-1
Tractability: Antibody: UniProt places it where antibodies can reach, with high confidence; UniProt predicts a signal peptide or a membrane-spanning region; its Gene Ontology location is reachable by antibodies, with medium confidence.
Gene: Protein-coding gene on chromosome 3 (68,004,247 to 68,545,621, forward strand). Ensembl gene ENSG00000183662.
Subcellular location: Secreted
Gene Ontology:
Molecular function: protein binding; receptor ligand activity
Biological process: neuroblast differentiation; regulation of neuroblast proliferation; regulation of signaling receptor activity; signal transduction
Cellular component: endoplasmic reticulum; extracellular region
Genetic constraint (gnomAD): Loss-of-function variants: 3 observed, 18.01 expected, observed/expected ratio (o/e) 0.17, 90% interval 0.075 to 0.43. The upper end of that interval is the gene's LOEUF score, 0.43, which puts it in group 1 of 6, group 1 being the genes least tolerant of losing a copy. Missense variants: 135 observed, 166.51 expected, observed/expected ratio (o/e) 0.81, 90% interval 0.7 to 0.94. Synonymous variants: 52 observed, 55.78 expected, observed/expected ratio (o/e) 0.93, 90% interval 0.75 to 1.17.
Homologues: Orthologues: chimpanzee TAFA1 (100% identical), guinea pig TAFA1 (100% identical), macaque TAFA1 (100% identical), dog TAFA1 (99% identical), mouse Tafa1 (99% identical), pig TAFA1 (99% identical), rat Tafa1 (99% identical), rabbit TAFA1 (98% identical), tropical clawed frog tafa1 (92% identical), zebrafish tafa1a (75% identical). Paralogues in human: TAFA3 (56% identical), TAFA4 (56% identical), TAFA2 (55% identical).
Diseases named in the same sentence as TAFA1 in open-access papers:
TAFA1 is named in the same sentence as 8 diseases in open-access papers, as found by Europe PMC text mining. Sharing a sentence is not in itself a finding about the gene and the disease. The quoted sentences say what the papers report.
neuronal tumor (2 papers, 2023 to 2024). Neuronal brain tumors are an uncommon group of central nervous system tumors that arise from cells with neuronal differentiation. "TAFA1, ALK, and VAV3 were some of the topmost DE genes in glioneuronal/neuronal tumors." (PMID 36865335, 2023).
TAFA1 also shares sentences with these, for which no sentence is quoted: Anxiety (2 papers); cancer (1); depression (1); Intellectual disability (1); neurodevelopmental disorder (1); Proteinopathies (1); psychiatric disorder (1).